TFE3 (transcription factor binding to IGHM enhancer 3)
Diseases named in the same sentence as TFE3 in open-access papers (continued):
Sharing a sentence is not in itself a finding about the gene and the disease.
PEComas (continued). "Also, our results provide preliminary evidence that increased activity of TFE3, achieved through either gene amplification or rearrangement or through protein overexpression, might define a distinct class of PEComas characterized by worse prognosis and a more aggressive behavior." (PMID 37448552, 2023). "In addition, an accumulating body of evidence indicated that PEComas with TFE3-rearrangement have distinct morphology and immunophenotype compared to those of conventional PEComa." (PMID 31103952, 2019). "An increasing number of TFE3 rearrangement-associated tumors, which might morphologically overlap with RCC, including TFE3 rearrangement-associated perivascular epithelioid cell tumors (PEComas) and melanotic Xp11.2 translocation cancer, have recently been reported." (PMID 27733182, 2016). "Although none of the TFE3-rearranged PEComas in the initial study occurred in the kidney, 35 of such tumors have since been found in this organ, making it the most frequent site for this neoplasm." (PMID 39410016, 2024). "Among TFE3-rearranged tumors arising in the kidney, most have been viewed as morphologically heterogeneous carcinomas staining for the tubular marker PAX8, whereas some others as mesenchymal neoplasms named PEComas." (PMID 39410016, 2024). "TFE3-rearranged PEComas, with few exceptions, are not seen in TSC patients, are more common in young people, and are typically found in the gynecologic, genitourinary, and gastrointestinal tracts, as well as soft tissue sites." (PMID 39026968, 2024). "Cathepsin-K is diffusely and strongly positive; ER and PR are frequently positive; TFE3 is positive in tumors with diffuse epithelioid and clear morphology; and S100, CD117, and less commonly CD10, may rarely be positive in PEComas." (PMID 39064514, 2024). "Overall, our results suggest a negative prognostic role in PEComas for TFE3 positivity broadly defined as either gene amplification or rearrangement, or only as protein overexpression." (PMID 37448552, 2023). "A second subset of PEComas characterized by their prominent alveolar growth pattern and lack of smooth muscle marker expression harbor TFE3 rearrangements." (PMID 37041531, 2023). "TFE3 and RAD51B gene rearrangements have been also described in a subset of PEComas." (PMID 36367123, 2023). "A locus-specific loss of heterozygosity in the PEComa but not in the sinonasal carcinoma was identified, suggesting the causative role of the splice mutation in the PEComa pathogenesis, because we excluded known pathogenetic pathways characteristic to PEComas (TSC1/2, TFE3, RAD51B)." (PMID 35419288, 2022). "These tumors strongly express diffuse positiveness for HMB-45 and TFE-3, whereas it is weakly positive or negative for SMA and negative for melan A. TFE 3-associated PEComas can be associated with prior history of chemotherapy." (PMID 35232443, 2022). "Although the contribution of TFE3 to the pathogenesis and progression of PEComas-NOS remains poorly understood, the assessment of the TFE3 gene status may be necessary for an accurate diagnosis and prognosis of PEComas-NOS." (PMID 25621681, 2015). "Furthermore, there have been some case reports of PEComas, including a renal epithelioid AML, with positive TFE3 immunolabeling and TFE3 gene fusions." (PMID 26246933, 2015). "However, there is a lack of clinical studies evaluating mTOR inhibitors in PEComas with or without TFE3 translocation." (PMID 40989692, 2025). "However, no studies have been conducted to compare the response to mTOR inhibitors in PEComas with and without TFE3 translocation." (PMID 39026968, 2024). "They supported this choice by noting that melanin pigment is much more frequently seen in renal rather than extrarenal TFE3-rearranged PEComas, suggesting the possibility that at least some of them may derive from a different cell of origin." (PMID 39410016, 2024). "A significant subset of PEComas show overexpression of MITF in the absence of TFE3 expression." (PMID 39759135, 2024).
PEComas (continued). "Together with prior reports, our results indicate that an increase in the activity of TFE3, not exclusively through TFE3 gene translocation, might be responsible for the worse prognosis of this subtype of PEComas." (PMID 37448552, 2023). "Fifth, in PEComas, a lack of TSC mutations may be offset by mutually exclusive TFE3 translocations with constitutive TFE3 activation." (PMID 37627070, 2023). "Both TFE3 and TFEB tRCCs may overlap with each other’s and with other RCCs’ morphologies, in particular with clear cell RCC, papillary RCC or, more rarely, clear cell papillary renal cell carcinomas as well as perivascular epithelioid cell tumors (PEComas)." (PMID 35886994, 2022). "However, there is no study assessing the response to mTOR inhibitors for PEComas with and without TFE3 translocation." (PMID 34680376, 2021). "The response of TFE3 gene-rearranged PEComas to mTOR inhibitors is not well defined, and." (PMID 32685651, 2020). "With moderate or strong expression and otherwise appropriate findings, even a single melanocytic marker is sufficient for the diagnosis, and myogenic differentiation may be completely absent, especially in TFE3-translocated PEComas." (PMID 31309284, 2020). "Unresectable malignant PEComas with TFE3 rearrangement have no recommended therapy to date." (PMID 33330059, 2020). "However, patients with TFE3-rearranged PEComas, which do not involve the TSC2 gene, will likely fail to respond to mTOR1 inhibitors." (PMID 31103952, 2019). "TFE3 is highly sensitive for TFE3-rearranged RCC (positive in 95% of cases), though it may also be overexpressed in other tumor types, such as epithelioid angiomyolipoma, paragangliomas, melanomas, perivascular epithelioid cell tumors, and adrenocortical carcinomas." (PMID 39851801, 2025). "Interestingly, these PEComas are characterized by the absence of more common mutations in the TSC1 and TSC2 genes, which also alter TFE3/TFEB regulation, upon which the pathogenesis may converge." (PMID 38386415, 2024). "In contrast to visceral PEComas, cutaneous PEComas do not harbor TFE gene fusions and consistently lack TFE3 expression." (PMID 32316685, 2020). "TFE3 expression is also seen in alveolar soft part sarcoma, melanotic Xp11 TRCs, Xp11 RCC, and rare PEComas that are negative for MiTF." (PMID 24735727, 2014).
alveolar soft part sarcoma (68 papers, 2008 to 2025). An alveolar soft part sarcoma occurring in adults. "TFE3 regulates genes involved in autophagy and cell growth, with mutations associated with kidney cancer and Alveolar Soft Part Sarcoma (ASPS)." (PMID 40141456, 2025). "ASPSCR1, through its fusion with TFE3, plays a pivotal role in the development of alveolar soft part sarcoma by acting as an aberrant transcriptional transactivator, leading to deregulated transcription and oncogenesis." (PMID 40297177, 2025). "ASPSCR1 gene, the interacting gene of EPI, can translocate with TFE3 gene and results in a ASPSCR1-TFE3 fusion protein, which causes the tumor hypoxia and angiogenesis in alveolar soft part sarcoma." (PMID 38662077, 2024). "Some cases of alveolar soft tissue sarcomas have been found to be caused by the fusion of ASPSCR1 and TFE3." (PMID 37510264, 2023). "Translocations and rearrangements of TFE3 and TFEB are associated with a rare subtype of kidney cancer termed translocation-renal cell carcinoma (tRCC) and alveolar soft part sarcomas (ASPS), a rare lung cancer variant." (PMID 35665902, 2022). "TFE3 fusions were originally identified in alveolar soft part sarcoma (ASPS), in the form of ASPSCR1-TFE3, which is generated by a t(X;17) translocation." (PMID 33921435, 2021). "Our data were consistent with the report that tumor cells in alveolar soft part sarcoma, a malignancy with known TFE3 fusion expression, exhibit TGF-β1-dependent, hypoxia-regulated cytoglobin stellate cell activation association protein (cytg/STAP)." (PMID 26872381, 2016). "A strong positive immunoreaction against TFE3 (nuclear staining) is characteristic for alveolar soft part sarcoma." (PMID 18593459, 2008). "Hence promiscuous promoter binding is a common property of TFE3 fusion proteins shared in both tRCC and alveolar soft part sarcoma." (PMID 40148585, 2025). "Diagnoses included ASPSCR1::TFE3 alveolar soft part sarcoma; WWTR1::CAMTA1 epithelioid hemangioendothelioma; INI-1 deficient epithelioid sarcoma; EWSR1::NR4A3 extra-skeletal myxoid chondrosarcoma; and low-grade ARHGAP23::FER spindle cell malignancy, a novel fusion-driven sarcoma." (PMID 39941809, 2025). "Moreover, TFE3 gene fusions have been identified in patients with alveolar soft part sarcoma, epithelioid hemangioendothelioma and hepatic perivascular epithelioid cell tumors." (PMID 31043173, 2019). "TFE3 is a known fusion partner in papillary renal cell carcinoma and alveolar soft part sarcoma." (PMID 21625565, 2011). "The t(X;17)(p11.2;q25) or TFE3-ASPL translocation RCC and alveolar soft part sarcoma (ASPS) contain the identical TFE3-ASPL fusion transcript; however, the t(X;17) translocation is consistently balanced (reciprocal) in the Xp11.2 translocation RCC and unbalanced in the ASPS." (PMID 19450277, 2009). "Immunohistochemical staining demonstrated strong and diffuse nuclear TFE3 positivity, supporting the diagnosis of alveolar soft part sarcoma (ASPS)." (PMID 40894409, 2025). "Lactate uptake by tumors feeds their oxidative metabolism and requires the importer MCT1, a marker of mitochondrial activity and stemness in cancer and a target gene of the fusion protein ASPSCR1/TFE3 in alveolar soft part sarcoma (ASPS)." (PMID 34294128, 2021). "S100 (−), Syn (−), Myogenin (−), Desmin (−), TFE3 (+), HMB45 (−), and Ki-67 (about 7% +) supported the diagnosis of alveolar soft part sarcoma." (PMID 36467475, 2022). "Given that a broad differential had been excluded, transcription factor E3 (TFE3) staining was performed and showed strong nuclear positivity confirming an alveolar soft part sarcoma." (PMID 28744773, 2019). "Tsuda and colleagues reported that gene fusions involving TFE3 can activate MET signaling; hence, they proposed that MET inhibitors may be potential candidates for managing alveolar soft part sarcoma." (PMID 40563544, 2025).
alveolar soft part sarcoma (continued). "Besides this, microenvironmental lactate uptake by tumors feeds their oxidative metabolism and demands the importer MCT1, a marker of mitochondrial activity and stemness in cancer and a target gene of the fusion protein ASP-SCR1/TFE3 in alveolar soft part sarcoma (ASPS)." (PMID 36232732, 2022). "Our case was negative for TFE3 rearrangement, but the correlated clinical and pathological features confirmed the diagnosis of primary Alveolar soft part sarcoma." (PMID 33026169, 2021). "Likewise, alveolar soft part sarcomas harbor an ASPSCR1-TFE3 fusion, leading to a chimeric protein with a stronger transcriptional activity than native TFE3." (PMID 32867178, 2020). "The t(X; 17) (p11.2; q25) or TFE3-ASPL translocation in RCC and alveolar soft part sarcoma (ASPS) contain the identical TFE3-ASPL fusion transcript; however, the t(X; 17) translocation is consistently balanced (reciprocal) in the Xp11.2 translocation RCC and unbalanced in the ASPS." (PMID 26415891, 2015). "TFE3 is involved in the TGF beta signaling pathway and promotes TGF beta effects and aberrant TFE3 transcription activity is involved in the pathogenesis of alveolar soft-part sarcoma (ASPS)." (PMID 24857913, 2014). "Alveolar soft part sarcoma (ASPS) often carries a translocation between ASPSCR1 and TFE3 genes, resulting in a fusion protein that transcriptionally upregulates MET." (PMID 37213274, 2023). "For human diseases, translocations involve TFE3 with several fusion gene partners, including PRCC, NONO, SFPQ, CLTC, and ASPL, in certain pediatric renal carcinomas and alveolar soft part sarcoma." (PMID 26872381, 2016). "Immunohistochemical and molecular analysis favored a diagnosis of Alveolar Soft Part Sarcoma (ASPS), though TFE3 gene-rearranged PEComa could not be completely excluded." (PMID 40176092, 2025). "ASPS is characterised by the pathognomonic unbalanced, non-reciprocal translocation t(X;17)(p11:q25), fusing the alveolar soft part sarcoma chromosome region candidate 1 (ASPSCR1) gene on chromosome 17 to the transcription factor binding to IGHM enhancer 3 (TFE3) gene on the X chromosome." (PMID 31722230, 2020).
renal carcinoma (37 papers, 2009 to 2026). A carcinoma arising from the epithelium of the renal parenchyma or the renal pelvis. "The molecularly defined renal carcinomas include TFE3-rearranged RCC, TFEB-altered RCC, ELOC-mutated RCC, FH-deficient and SDH-deficient RCC, ALK-rearranged RCC, and SMARCB1-deficient renal medullary carcinomas." (PMID 38235567, 2024). "In the 2004 WHO classification of renal tumours, renal carcinoma associated with Xp11.2 translocational/TFE3 gene fusions (Xp11.2 translocation RCCs) was first accepted as a distinct subtype of RCC." (PMID 35850864, 2022). "Renal carcinoma associated with Xp11.2 translocations/TFE3 gene fusions is an unusual renal tumor, which is recognized as an entity in 2004 WHO classification of tumors of the urinary system." (PMID 31828108, 2019). "This study was to investigate the features of renal carcinomas associated with Xp11.2 translocations/TFE3 gene fusions (Xp11.2-RCC) on conventional ultrasound (US) and contrast-enhanced ultrasound (CEUS)." (PMID 29333109, 2017). "While positive staining for the TFE3 gene in immunohistochemical examinations has been a hallmark of renal carcinoma with TFE3 gene fusion, the diagnosis is now confirmed through more precise gene karyotype detection and FISH analysis using paraffin-embedded sections or formalin-fixed tissue." (PMID 39851801, 2025). "Lastly, pediatric PEComas of the urinary system sometimes may be confused with renal carcinoma associated with Xp11.2 translocations/TFE3 gene fusions, which usually affect children and young adults." (PMID 23276164, 2012). "We define tRCC as a novel metabolic subtype of renal cancer and provide unique insights into how broad genomic binding of TFE3 fusion proteins regulates OxPhos and ferroptosis resistance." (PMID 40148585, 2025). "The most important immunohistochemical marker in differentiating renal carcinoma with Xp11.2 translocation from other types remains positive staining for the TFE3 protein." (PMID 39851801, 2025). "Renal carcinoma with Xp11.2 translocation involving TFE3 gene fusion presents variable clinical manifestations compared to conventional renal cancers, most likely due to the heterogenicity of the tissue structure." (PMID 39851801, 2025). "This pattern is highly suggestive of secondary lymph node involvement of renal carcinoma with Xp11.2 translocation, involving TFE3 gene fusion." (PMID 39851801, 2025). "If this is not identified, the differential diagnosis becomes more challenging, but previous studies have identified some specific immunohistochemical patterns for renal carcinoma with TFE3 gene fusion." (PMID 39851801, 2025). "The main features of this type of renal cancer, as stated by its name, are fusions involving the TFE3 gene, situated on chromosome Xp11.2, resulting in the overexpression of the TFE3 protein within the nuclei of cancer cells." (PMID 39851801, 2025). "Collectively, these data suggest that while nuclear activation of TFE family members has an oncogenic function in renal cancer generally, TFE3 oncofusion proteins are specifically required to mediate malignant transformation in tRCC." (PMID 41027885, 2025). "The specific immunohistochemical marker for this type of renal carcinoma is positive staining for the TFE3 protein." (PMID 39851801, 2025). "In 2004, WHO classified Xp11.2/TFE3 translocation RCC as an independent subtype of renal carcinoma, and in 2016, it was reclassified as microphthalmia‐associated transcription factor (MiTF) RCC subtype." (PMID 38477529, 2024). "Histologically, TFE3‐rearranged RCC is difficult to differentiate from other renal carcinoma subtypes." (PMID 38477529, 2024). "Accordingly, mTORC1 inhibition or silencing of TFE3 or Rag D reduces mTORC1 activity and proliferation of renal cancer cells expressing TFE3 fusions." (PMID 33981707, 2021). "TFE3 knockdown reduced GPNMB expression in renal cancer cells harboring either TFE3 translocations or FLCN inactivation." (PMID 21209915, 2010).